APOA4 (apolipoprotein A4)
Diseases named in the same sentence as APOA4 in open-access papers (continued):
Sharing a sentence is not in itself a finding about the gene and the disease.
celiac disease (4 papers, 2019 to 2023). An autoimmune genetic disorder with an unknown pattern of inheritance that primarily affects the digestive tract. "In our study, APOA4 staining improved the reliability and reproducibility of VH : CrD measurements in celiac disease biopsy specimens in comparison to traditional H&E-stained sections." (PMID 34394117, 2021). "The addition of APOA4 staining to the immunohistochemistry workout is relatively easy because CD3 IHC staining of IELs is included routinely in translational celiac disease studies and clinical trials." (PMID 34394117, 2021). "Previously, we showed that the mRNA expression levels of APOA4 are decreased in untreated celiac disease and after gluten challenge." (PMID 34394117, 2021). "To exemplify this, we analysed the mRNA levels of two genes whose expression is correlated with coeliac disease mucosal damage, namely, APOA4 and Ki67, by RT-qPCR and RNAseq." (PMID 31730447, 2019). "These markers, and especially the villous:crypt ratio of these two parameters, APOA4/Ki67, appeared to measure coeliac disease activity well in the gluten challenge." (PMID 31730447, 2019). "Hence, APOA4 staining can be used as an objective marker of the villus-crypt border in analysis of the duodenal mucosal architecture in celiac disease." (PMID 34394117, 2021). "Hence, these results present the gluten-induced changes that occur in molecular VH (APO4), CrD (Ki67) and VH: CrD (APOA4/Ki67) alongside the architectural mucosal changes in coeliac disease." (PMID 31730447, 2019). "Strengths of the study include the use of samples comprising a spectrum of celiac disease severity and the use of immunohistochemical stains to evaluate individual cellular (e.g., CD3) and tissue specific (e.g., ApoA4) features of the resulting CNN overlay images to confirm classifier accuracy." (PMID 37951937, 2023). "APOA4 staining is easy to perform and allows coordinated analysis of the duodenal mucosa in celiac disease that has not been possible before." (PMID 34394117, 2021). "Immunohistochemistry further demonstrated reduced epithelial abundance of APOA4 protein that also showed a reduced expression in our dataset in the cytoplasm and SI in the brush border in active celiac disease patients in comparison to non-celiac subjects." (PMID 31700112, 2019).
colorectal cancer (4 papers, 2016 to 2025). A primary or metastatic malignant neoplasm that affects the colon or rectum. "Previous studies reported the association of aberrant APOA4 expression with colorectal cancer development in diabetic patients and a reduced plasma abundance in colorectal cancer patients." (PMID 32545216, 2020). "Using a machine learning approach, we determined that the combination of LRG1 and APOA4 serves as the most effective predictive plasma marker for colorectal cancer." (PMID 38735538, 2024). "We also found that the combination of leucine-rich α-2 glycoprotein 1 (LRG1) and apolipoprotein A4 (APOA4) had the best predictive ability for colorectal cancer and has the potential to be a biomarker." (PMID 38735538, 2024). "Immunoblotting results demonstrated high expression of plasma LRG1 and low expression of APOA4 in colorectal cancer, further validating the results of plasma quantitative proteomics." (PMID 38735538, 2024). "Notably, several significantly altered proteins, including APOA4, CLU, and SAA4, have previously been reported as potential biomarkers for colorectal cancer." (PMID 41367384, 2025).
gastric cancer (4 papers, 2015 to 2023). A primary or metastatic malignant neoplasm involving the stomach. "These aptamers were used for detecting APOA1, Importin subunit alpha-1, PARD3, and APOA4 gastric cancer biomarkers; where Importin subunit alpha-1 is the strongest candidate to be used for further gastric cancer diagnosis." (PMID 32659966, 2020). "Serum APOA4 is a reported marker of pancreatic and ovarian cancers, and it is differentially expressed in the sera of gastric cancer patients." (PMID 25915536, 2015). "Low expression of apolipoproteins including APOA1, APOA2, APOA4 and APOC3 in plasma exosomes of patients with hepatic-specific metastasis indicated an impaired function of lipid metabolism, which could participate in hepatic metastasis in gastric cancer cells." (PMID 37568802, 2023).
Hypertension (4 papers, 2016 to 2022). The presence of chronic increased pressure in the systemic arterial system. "For instance, decreased APOA4, APOC1, and APOC3 expression would result in reduced lipid removal from the vascular wall and inhibition of lipoprotein lipase activity, potentially promoting lipid accumulation, which might be associated with hypertension." (PMID 34929167, 2022).
pancreatitis (4 papers, 2017 to 2025). Inflammation of the pancreas. "Four proteins (APOA4, APOC3, IGFBP2 and TIMP1) were significantly altered in PC compared with healthy subjects or pancreatitis using Kruskal-Wallis test (P < 0.01)." (PMID 28514751, 2017). "The higher level of TIMP1, the lower the level of APOA4, APOC3 and IGFBP2 in PC, compared with healthy controls or patients with pancreatitis." (PMID 28514751, 2017). "Based on the results, apolipoprotein A-IV (APOA4), apolipoprotein C-III, IGFBP2 and tissue inhibitor of metalloproteinase 1 (TIMP1) were found significantly altered in the serum of PDAC patients (stage I–IV) compared to those with pancreatitis as well as healthy controls." (PMID 35216204, 2022). "Of these marker combinations, a biomarker panel consisting of CA19-9, APOA4 and TIMP 1 [AUCpanel > 0.934 (95% CI: 0.877–0.970), SN/SP of 86%/90%] demonstrated better performance than any other biomarker panels, or CA 19-9 alone, for distinguishing early PC from pancreatitis." (PMID 28514751, 2017).
Sepsis (4 papers, 2020 to 2025). Sepsis is defined as life-threatening organ dysfunction caused by a dysregulated host response to infection. "The downregulation of APOA4 aligns with patterns previously observed in adult sepsis, where decreases in apolipoproteins are thought to reflect inflammation induced disruption of lipid transport and metabolism." (PMID 40927580, 2025).
adenoma (3 papers, 2023 to 2025). A neoplasm arising from the epithelium. "Based on the consistency of their expression changes in the adenoma groups across both cohorts and their differential expression between inflammatory polyps and adenomas, we selected APOA4 and FLNA for further investigation, while excluding FERMT3 and THBS1." (PMID 41367384, 2025). "Six genes (SAA2, SAA1, CRP, SAA3P, PLA2G2A, and APOA4) listed in the heat map also indicated that the expression of PLA2G2A was limited to the adenoma tissue, following the violin plot results." (PMID 38201587, 2023). "Among these, APOA4, FERMT3, and FLNA exhibited consistent expression changes in the adenoma groups of both cohorts." (PMID 41367384, 2025). "Additionally, APOA4 and FLNA levels differed significantly between inflammatory polyps and adenomas in at least one cohort." (PMID 41367384, 2025). "To validate APOA4 and FLNA as potential biomarkers, we conducted an independent validation study in cohort 3, including 37 healthy controls (H), 38 inflammatory polyp patients (A), and 45 adenoma patients (B)." (PMID 41367384, 2025). "Likewise, considering the variable importance values obtained, LOC399753, APOA4, MIR548X, and ADH1C genes can be used to differentiate duodenal cancer patients with FAP from the adenoma tissues of non-cancer patients with only FAP for adenoma–adenoma comparison." (PMID 37565794, 2023).
Cirrhosis (3 papers, 2020 to 2024). A chronic disorder of the liver in which liver tissue becomes scarred and is partially replaced by regenerative nodules and fibrotic tissue resulting in loss of liver function. "Apolipoprotein A4 is the glycoprotein in our study which shows down-regulated expression in advanced cirrhosis based on HCV." (PMID 33585012, 2020). "Our hypothesis is that the decreased apolipoprotein A4 levels in advanced cirrhosis-based HCV might be explained by changes in the synthesis of enzyme in lipid metabolism." (PMID 33585012, 2020). "Also, lower expression of APOA4 and the other spot of HP in advanced cirrhosis patients were revealed based on HCV compared to matched controls." (PMID 33585012, 2020).
diabetic kidney disease (3 papers, 2020 to 2023). Progressive kidney disorder caused by vascular damage to the glomerular capillaries, in patients with diabetes mellitus. "PromarkerD is a proteomics derived test for predicting diabetic kidney disease that measures the concentrations of three plasma protein biomarkers, APOA4, CD5L and IBP3." (PMID 33126588, 2020). "Studies have shown that ApoA4 levels are elevated in DM patients and may be a potential biomarker for DM and diabetic nephropathy." (PMID 37667364, 2023).
breast carcinoma (2 papers, 2019 to 2021). "While there is no known association between APOA4 and breast cancer risk, two plausible candidates (ZNF259 and BUD13) map approximately 42 kb and 57 kb centromeric to the 11q23.3 breakpoint." (PMID 30496607, 2019). "We further examined the prognostic values of the mRNA expressions of APOA1, APOC3, APOA4, and APOA5 by using two online survival analysis software packages that were established through analyses of predominantly Western patients with breast cancer." (PMID 34226567, 2021).
depression (2 papers, 2020 to 2025). "Data-driven analysis showed that ApoA4 has very high accuracy for discriminating individuals with remitted late-life depression (LLD) compared to never-depressed control participants." (PMID 32795354, 2020).
gestational hypertension (2 papers, 2022 to 2026). "The profile differentiating gestational hypertension (GAH) from chronic hypertension (CAH) was linked to lipid metabolism (HRG, APOA4, APOC2)." (PMID 41683823, 2026).
lipid metabolic disorders (2 papers, 2022 to 2024). "Interestingly, the members of PPAR signaling pathway, APOA1 and PCK1 were often enriched in biological processes involved in lipid metabolism together with APOA4, and were related to lipid metabolic disorders." (PMID 38665091, 2024). "In this study, APOA4 and APOB were significantly downregulated in SBA, suggesting that lipid metabolism disorders may play an important role in the occurrence of SBA." (PMID 36171259, 2022).
mastitis (2 papers, 2019 to 2022). Inflammation of breast tissue during lactation or postpartum due to an obstructed duct or infection. "Therefore, whether APOA4 plays an important role in regulating immune response during sheep mastitis, which remains to be fully elucidated." (PMID 31159303, 2019). "However, we found that APOA1, APOA4, APOE, and RBP4 were downregulated during clinical mastitis." (PMID 36335251, 2022).
abetalipoproteinemia (1 paper, 2023). "Also, in patients with abetalipoproteinemia, a genetic disorder in which chylomicrons and other APOB lipoproteins are not synthesized, APOA4 is still detected on small HDL, but not on large HDL, suggesting that the presence of APOA4 on large HDL may be dependent on chylomicron production." (PMID 37092549, 2023).
acute liver failure (1 paper, 2021). Rapid deterioration of liver function causing encephalopathy and coagulopathy. "Serum APOA4 levels were increased after rh-HGF administration, not only in normal mice but also in anti-Fas-induced murine acute liver failure (ALF), which confirmed the pharmacodynamic nature of APOA4." (PMID 33925510, 2021).
Atrophy (1 paper, 2021). Any weakening or degeneration, especially through lack of use. "In damaged mucosa, long crypt basins can be misread as villi in H&E staining, but with the aid of APOA4 staining, it can be seen that the crypt extends up close to the lumen, resulting in a histological diagnosis of total villous atrophy in both cases." (PMID 34394117, 2021).
Cachexia (1 paper, 2022). Severe weight loss, wasting of muscle, loss of appetite, and general debility related to a chronic disease. "Of the six proteins that showed significant differences between the patients with and without cachexia, three were lower (CNPD1, APOA4, DACH1) while three were higher (BCL3 NARS2, ATP13A4) in cachexia." (PMID 36080280, 2022).
cataract (1 paper, 2021). Partial or complete opacity of the crystalline lens of one or both eyes that decreases visual acuity and eventually results in blindness. "Conversely, female POAG patients had significantly greater levels of APOA1 (FC = 1.36; p < 0.01), APOA2 (FC = 1.21; p = 0.03), APOA4 (FC = 1.30; p = 0.04), APOC3 (FC = 1.38; p = 0.01), and APOD (FC = 1.20; p = 0.04) compared to cataract patients." (PMID 34602085, 2021).
cognitive deficits (1 paper, 2025). "Moreover, deficiency of APOA4 promotes β-amyloid formation and results in cognitive deficits, suggesting a higher abundance of apolipoprotein A4 may be favored for preserving cognitive functions." (PMID 40502786, 2025).
congenital cataracts (1 paper, 2022). "Group 5 (congenital cataracts) also shows abundant proteins involved in protein metabolism, among which three proteins—corticosteroid-binding globulin-SERPINA6, apolipoprotein A-IV (APOA4), and inter-alpha-trypsin inhibitor heavy chain H4 (ITIH4)—were downregulated compared to other groups." (PMID 36362243, 2022).
diabetic macular edema (1 paper, 2015). "Also, in the vitreous of diabetic macular edema, APOA-4 and other pigment epithelium-derived factor, like APOA-4, APOA-1, trip-11, and RBP were elevated." (PMID 26608305, 2015).
endometrial cancer (1 paper, 2024). Primary or metastatic malignant neoplasm involving the endometrium (mucous membrane that lines the endometrial cavity). "APOA4 was downregulated in endometrial cancer patients, while C4A and C3 were upregulated." (PMID 39194522, 2024). "Six of them were upregulated in endometrial cancer patients (CLU, SERPINC1, ITIH4, C1RL, APOC3 and DSC1), while ten were downregulated (APCS, C9, APOA1, ALB, APOA4, CFHR1, ITIH2, and ACTB)." (PMID 39194522, 2024).
endometrial neoplasm (1 paper, 2016). Tumors or cancer of ENDOMETRIUM, the mucous lining of the UTERUS. "Interestingly, the levels of APOA4 have been similarly shown to be able to discriminate malignant from benign cases in ovarian and endometrial neoplasms." (PMID 27672505, 2016).
epilepsy (1 paper, 2024). A brain disorder characterized by episodes of abnormally increased neuronal discharge resulting in transient episodes of sensory or motor neurological dysfunction, or psychic dysfunction. "In our study, an increased expression of APOA4 was found in the epilepsy group." (PMID 39063177, 2024).
gastric adenocarcinoma (1 paper, 2024). "For instance, the lncRNA-mRNA network constructed in gastric adenocarcinoma has shown the possible role of the AC115619.1-APOA4/APOB and AP006216.2-APOA1/APOA4 axes in the pathogenesis of this cancer through regulation of fat digestion and absorption as well as vitamin digestion and absorption." (PMID 38475720, 2024).
glioma (1 paper, 2021). A benign or malignant brain and spinal cord tumor that arises from glial cells (astrocytes, oligodendrocytes, ependymal cells). "Our own work identified APOA1 and APOA4 in the proteomic analyses of EVs derived from human medulloblastoma cell lines and murine glioma cells, with APOB and APOE identified in EVs from other tumor cell lines (Graner, unpublished data)." (PMID 34360613, 2021).
hepatitis B virus infection (1 paper, 2023). A viral infection caused by the hepatitis B virus. "In humans, APOA4 is upregulated in severe adenovirus community-acquired pneumonia, and plasma concentrations of the protein increase in inflammatory disorders during hepatitis B virus infections." (PMID 38193073, 2023).
hepatitis C (1 paper, 2018). "Two proteins that demonstrated significance by LMM(RF) and LMM(RR) were also previously reported: CD5L (CD5 antigen-like), reported as differentially expressed in hepatitis C patients: and APOA4, (apolipoprotein A-IV), reported as misexpressed in liver metabolic disorders." (PMID 30598095, 2018).
hypercoagulable (1 paper, 2021). "This indicates that the content of APOA4, which inhibits thrombus formation, would decrease during the hypercoagulable state." (PMID 33996895, 2021). "In the ETSL-induced hypercoagulable state model, the APOA4 level in urine significantly decreased." (PMID 33996895, 2021). "Therefore, we speculate that the decrease of APOA4 content in urine is due to the decrease of its expression during the hypercoagulable state." (PMID 33996895, 2021).
Hyperhidrosis (1 paper, 2023). Abnormal excessive perspiration (sweating) despite the lack of appropriate stimuli like hot and humid weather. "As the DHS group showed lower APOA4 and higher pantothenic, it is understandable that non-DHS patients feature sleep hyperhidrosis, fatigue, as well as joint disorders." (PMID 37304842, 2023).
Infertility (1 paper, 2025). "Also, menstrual blood serum was characterized as a less invasive source of infertility biomarkers, where EMILIN1, TRIP6, LAMB1, LAMC1, NID1, APOB, APOA4 were detected as the main differences in uIF patients as compared to healthy controls." (PMID 40861859, 2025).
iron deficiency (1 paper, 2013). "As expected, hepcidin was down- and up-regulated in iron deficiency and overload respectively, and genes such as Ccdn1 and Apoa4 were modulated according to the iron/hepcidin levels, as already reported." (PMID 23922777, 2013).
papillary thyroid carcinoma (1 paper, 2024). "Concerning APOA4, several proteomics studies have identified low levels, which were associated with various forms of cancer, including epithelial ovarian, hepatocellular, pancreatic, oral and papillary thyroid carcinoma." (PMID 39194522, 2024).
small bowel adenocarcinoma (1 paper, 2022). "Four target genes (APOA4, APOB, COL1A2, FN1) may be involved in the pathogenesis of small bowel adenocarcinoma." (PMID 36171259, 2022).
squamous cell carcinomas of the lung (1 paper, 2023). "While enhanced APOA4 expression was reported in squamous cell carcinomas of the lung, in adenocarcinomas, a loss of APOA4 was reported in serum, which is comparable with previous findings from similar studies." (PMID 38067270, 2023).
temporal lobe epilepsy (1 paper, 2024). A localization-related (focal) form of epilepsy characterized by recurrent seizures that arise from foci within the temporal lobe, most commonly from its mesial aspect. "Several apolipoproteins (APOA1, APOD, and APOA4), serpin protease inhibitors (SERPINA3, SERPINF1, etc.), complement components (C9, C8, and C1R), and a total of 42 proteins were found to be significantly upregulated in the temporal lobe epilepsy group." (PMID 39063177, 2024).
thyroid cancer (1 paper, 2023). "APOA1, APOA2, and APOA4 were found to be downregulated in female patients with thyroid cancer." (PMID 38067270, 2023). "Other contradicting findings stated that APOA1 and APOA4 were overexpressed in PTC, the most prevalent subtype of thyroid cancer, when a proteome analysis was conducted on PTC cells." (PMID 38067270, 2023).
transmissible spongiform encephalopathies (1 paper, 2011). "Several studies have also reported the involvement of many members of the apolipoprotein gene family (ApoA1, ApoA4, ApoC1, ApoC2, ApoC3 and ApoD) in transmissible spongiform encephalopathies." (PMID 21629698, 2011).
urinary bladder cancer (1 paper, 2020). A primary or metastatic malignant neoplasm involving the bladder. "APOA4 was reported to be closely related to urinary bladder cancer." (PMID 32547867, 2020).
urothelial carcinoma (1 paper, 2025). A malignant neoplasm derived from the transitional epithelium of the urinary tract (urinary bladder, ureter, urethra, or renal pelvis). "A biomarker panel comprising Stathmin-1, DJ-1/PARK7, Gamma-synuclein, and APOA4 reliably distinguished urothelial carcinoma from benign urothelium." (PMID 41357584, 2025).